MAGI1 (membrane associated guanylate kinase, WW and PDZ domain containing 1)
Diseases named in the same sentence as MAGI1 in open-access papers (continued):
Sharing a sentence is not in itself a finding about the gene and the disease.
tumor (continued). "Although the functional role of MAGI1 phosphorylation at Tyr373 currently remains unclear, PTEN is known to cooperate with MAGI1 proteins in order to block PI3 kinase-AKT, which is important for stabilizing of cell-cell contacts and suppressing of tumor invasiveness." (PMID 26857455, 2016). "Additionally, we prove that MAGI1 mRNA levels are upregulated after treatment with histone deacetylase (HDAC) inhibitors in different BC cell lines, which suggests that histone deacetylation could be part of the mechanisms that downregulate MAGI1 during tumor progression." (PMID 37566008, 2023). "The case 1 with the non-frameshift insertion of both MAGI1 and SLC45A3 was died 27 months after the operation because of metastases to the liver and bone, while the molecular mechanism of MAGI1 and SLC45A3 to the cervical grade 2 tumor of this case is sill unknown and need to further study." (PMID 31228945, 2019).
cancer (20 papers, 2008 to 2025). A tumor composed of atypical neoplastic, often pleomorphic cells that invade other tissues. "It is important to unravel the signaling pathways and mechanisms that induce MAGI1 loss in different cancer types." (PMID 34198584, 2021). "MAGI1-specific mechanisms that regulate its expression, and in particular cause or contribute to its downregulation in cancer cells, remain largely to be elucidated." (PMID 34198584, 2021). "We found that somatic genomic alterations of the RECQL4, JAK3, ARID1A, and MAGI1 genes, combined with MBs, were associated with the development of metachronous cancers after curative ESD and successful HP eradiation." (PMID 33328548, 2020). "Taken together, these results indicate that low levels of MAGI1 promote lung metastasis of ER+ 67NR cells and this effect is associated with enhanced early survival (i.e., 48 hours’ time point) of disseminated cancer cells." (PMID 31963297, 2020). "A recurring question concerns the mechanism of MAGI1 downregulation in a subset of ER+HER2− cancers." (PMID 37566008, 2023). "Our findings provide a new view on MAGI1 function in cancer and identify potential treatment options to improve the management of ER+ BC patients with low MAGI1 levels." (PMID 37566008, 2023). "In this review, we have highlighted the current knowledge on MAGI1 functions in epithelial, endothelial, and cancer cells." (PMID 34198584, 2021). "Thirdly, reduced MAGI1 expression in ER+/HER2− cancer correlates with inflammation, based both on human transcriptomic and experimental data." (PMID 31963297, 2020). "Secondly, experimental data demonstrate that downregulation of MAGI1 in ER+/HER2− cancer cells generates a more aggressive cancer cell phenotype." (PMID 31963297, 2020). "A number of MAGI1 physiological functions and involvements in pathologies, including cancer, have been reported, but only little is known on the putative function of MAGI1 in vascular biology." (PMID 31035633, 2019). "Expression of a form of MAGI-1 resistant to E6-mediated degradation represses cancer cell proliferation and induces apoptosis." (PMID 27537218, 2016). "PGE2 was shown to suppress MAGI1 expression in cancer cells." (PMID 34198584, 2021). "Taken together, these results show that the loss of MAGI1 in luminal BCa cells promotes cancer cell proliferation and anchorage-independent growth, but not migration/invasion." (PMID 33707576, 2021). "Taking into consideration the role of chronic inflammation and PGE2 in cancer development and progression, including in BC, we therefore sought to study whether MAGI1 expression was possibly modulated by PGE2 or COXIB in BC." (PMID 31963297, 2020). "In addition, studies have shown that MAGI1 inhibits cancer cell migration and invasion in HCC." (PMID 34422806, 2021). "Thus, the signaling mechanisms that we have identified in this work should be evaluated in future work to determine whether modulation of p90RSK-MAGI1 and MAGI1 mediated signaling has therapeutic potential in cancer models." (PMID 33304925, 2020). "MAGI1 participates in regulating oncogenic pathways such as the PI3K/AKT and the Wnt/β-catenin pathways, however, the mechanisms of its downregulation in cancer remain mostly elusive." (PMID 34198584, 2021). "In this study, somatic alterations of two cancer-related genes, including the RECQL4 and the JAK3, had significant associations with non-MGC development, and the ARID1A and the MAGI1 genes had significant associations with metachronous development." (PMID 33328548, 2020). "While it is clear that MAGI1 expression is reduced during cancer progression, it is not clear yet whether MAGI1 levels may be used to stratify cancer patients for prognostic purposes and, more importantly, for therapeutic decisions." (PMID 34198584, 2021).
infection (5 papers, 2011 to 2022). The state of being infected such as from the introduction of a foreign agent such as serum, vaccine, antigenic substance or organism. "After 24 h of infection, the cells were lysed, total RNA was extracted and analyzed by qRT-PCR to determine relative changes in Magi1 mRNA expression levels." (PMID 36082118, 2022). "A549 cells were infected with either the wt NS1 or mutant ESEA virus and localization of NS1 and MAGI-1 was examined at 24 hours post-infection." (PMID 22911767, 2012). "We also observed that expression of the ESEV NS1 protein during infection perturbs the plasma membrane localization of MAGI-1." (PMID 22911767, 2012). "Specifically, infection of MAGI1-null ECs with IAV upregulates expression of signal transducer and activator of transcription 1 (STAT1), interferon b1 (IFNb1), myxovirus resistance protein 1 (MX1) and 2′-5′-oligoadenylate synthetase 2 (OAS2), and activate STAT5." (PMID 36082118, 2022). "- MAGI1 depletion upregulates anti-viral response including STATs and IRF3 activation and inhibits EC infection by IAV." (PMID 36082118, 2022). "These new interactions can provide interesting starting points for exploration of potential new in vivo functions of MAGI1 and SCRIB that might be perturbed upon infection with HPV." (PMID 22069443, 2011). "Therefore, it would be important to better understand the signalling pathways, such as those of cell growth and apoptosis, that are regulated by MAGI1 and SCRIB and that are disrupted upon infection with oncoviruses such as HPV." (PMID 22069443, 2011).
cardiovascular diseases (3 papers, 2019 to 2022). "Therefore, the inhibition of MAGI1 is a potential therapeutic target for IAV-induced cardiovascular disease." (PMID 36082118, 2022). "The aim of the study was to test the hypothesis that MAGI1 drives EC activation after IAV infection, and that this process promotes IAV-mediated cardiovascular disease." (PMID 36082118, 2022). "Together, these results show that MAGI1 could be the molecular link between IAV infection and cardiovascular disease." (PMID 36082118, 2022).
adenocarcinoma (1 paper, 2020). A common cancer characterized by the presence of malignant glandular cells. "For this we used two sister-cell lines derived from a mouse adenocarcinoma model in BALB/c with different MAGI1 expression levels and metastatic capacities: 67NR (ER+) being non-metastatic and 4T1 (ER−), highly metastatic." (PMID 31963297, 2020).
psychiatric disorder (1 paper, 2021). A disorder characterized by behavioral and/or psychological abnormalities, often accompanied by physical symptoms. "MAGI1 also regulates the traffic of corticotropin-releasing factor receptor 1 (CRFR1), a receptor implicated in some psychiatric disorders." (PMID 34198584, 2021). "In addition, expression differences of MAGI1 in bipolar cases versus control subjects have also been reported, findings that support that MAGI1 might also be important for brain function in psychiatric disorders." (PMID 34198584, 2021).
MAGI1 also shares sentences with these, for which no sentence is quoted: hepatocellular carcinoma (7 papers); Hypertension (2); microscopic colitis (2); anaplastic thyroid cancer (1); autism (1); bladder cancer (1); celiac disease (1); cervical tumor (1); colon (1); epilepsy (1); estrogen-receptor positive breast cancer (1); glomerulosclerosis (1); immune diseases (1); inflammatory bowel disease (1); influenza (1); invasive carcinoma (1); lung adenocarcinoma (1); lung carcinoma (1); major depression (1); psoriasis (1); psychosis (1); renal papillary cell carcinoma (1); schizoaffective disorder (1); squamous intraepithelial lesion (1); systemic scleroderma (1); thyroid carcinoma (1); triple-negative breast carcinoma (1); ulcerative colitis (1).